RNF128 (ring finger protein 128)
Diseases named in the same sentence as RNF128 in open-access papers (continued):
Sharing a sentence is not in itself a finding about the gene and the disease.
colitis (1 paper, 2025). Inflammation of the colon. "Bone marrow transplantation experiments revealed that RNF128 deficiency in bone marrow cells contributes to the worsening of DSS-induced colitis." (PMID 39809743, 2025). "Rnf128 deficiency substantially increased macrophage infiltration in colonic tissues during colitis." (PMID 39809743, 2025). "In summary, we demonstrated for the first time that macrophage RNF128 deficiency promotes colitis progression by suppressing Tollip-mediated autophagic degradation of S100A8." (PMID 39809743, 2025). "A recent study reported that RNF128 deficiency in intestinal epithelial cells promoted colitis and colorectal tumorigenesis by activating IL-6-STAT3 signaling." (PMID 39809743, 2025). "We conducted a bone marrow transfer experiment to determine whether RNF128 deficiency in macrophages contributes to the aggravation of DSS-induced colitis." (PMID 39809743, 2025). "Interestingly, a recent study reported that RNF128 deficiency in intestinal epithelial cells promoted colitis and colorectal tumorigenesis by interacting with IL-6Rα and glycoprotein gp130." (PMID 39809743, 2025). "We also established an acute colitis mice model and observed that Rnf128 expression was markedly lower in colitis tissues than that in normal tissues." (PMID 39809743, 2025). "Overall, our study underscores the anti-inflammatory role of RNF128 in macrophages during the progression of colitis and highlights the potential of targeting the RNF128-Tollip-S100A8 axis to attenuate intestinal inflammation for the treatment of colitis." (PMID 39809743, 2025). "Our findings underscore the protective roles of RNF128 in colitis and contribute to the understanding of S100A8 regulation." (PMID 39809743, 2025). "Intravenous injection of RNF128-overexpressing T cells significantly alleviated the severity of colitis in a mouse model." (PMID 39809743, 2025). "To identify the underlying molecular mechanism responsible for the protective role of RNF128 in colitis, we performed an immunoprecipitation-coupled mass spectrometry screen." (PMID 39809743, 2025). "To determine the role of RNF128 in colitis, we generated Rnf128 knockout (Rnf128−/−) mice and established an acute colitis model by challenging Rnf128+/+ and Rnf128−/− mice with 2.5% DSS." (PMID 39809743, 2025). "Although our study demonstrated the protective role of macrophage RNF128 in colitis and its underlying molecular mechanism, the reasons for the reduced expression of RNF128 in macrophages during colitis remain unclear, suggesting a novel research direction." (PMID 39809743, 2025). "Additionally, the Rnf128−/−→Rnf128+/+ group presented increased macrophage infiltration, fewer Ki67-positive cells and higher levels of proinflammatory cytokines (Il-1β and Tnf-α) in the serum of the mice with colitis than the Rnf128+/+→ Rnf128+/+ group." (PMID 39809743, 2025). "However, Rnf128−/− mice exhibited more severe intestinal inflammation in the DSS-induced colitis model, as evidenced by shorter colon length, increased weight loss and higher disease activity index." (PMID 39809743, 2025). "Thus, we conclude that RNF128 from different cell sources plays a protective role in colitis." (PMID 39809743, 2025). "Moreover, RNF128 expression was lower in the PBMCs of IBD patients and the BMDMs of colitis mice than in those of healthy individuals or control mice." (PMID 39809743, 2025). "Considering previous results that RNF128 is primarily localized in macrophages, we speculate that macrophage RNF128 plays important roles in mediating resistance to DSS-induced colitis." (PMID 39809743, 2025).
COVID-19 (1 paper, 2023). A disease caused by infection with severe acute respiratory syndrome coronavirus 2. "It would be interesting to determine whether RNF128 expression is elevated in COVID-19 patients and whether RNF128 overexpression attenuates COVID-19-induced inflammation." (PMID 37344492, 2023).
diabetes (1 paper, 2013). "We also checked the genes RNF128 and MAFA, which were ranked at top 1 and top 2 for diabetes, respectively." (PMID 24344781, 2013).
dysferlinopathy (1 paper, 2022). "Significantly low expression of RNF128 in dysferlinopathy may lead to increased production of cytokines, and cause muscle inflammation." (PMID 36203997, 2022). "In both datasets, MVP, GRN, and ERP29 showed significantly higher expression levels, while RNF128, NFYB, and KPNA3 had significantly lower expression levels in dysferlinopathy than normal controls." (PMID 36203997, 2022). "Consistent with the two datasets, MVP, GRN, and ERP29 expression were significantly upregulated, and RNF128, NFYB, and KPNA3 were significantly downregulated in the dysferlinopathy patients compared with the controls." (PMID 36203997, 2022).
lung carcinoma (1 paper, 2021). "RNF128 can also bind other E3 ubiquitin ligases, such as NEDD4, to promote the migration of lung cancer cells." (PMID 33962392, 2021).
Lymphatic Metastasis (1 paper, 2019). Transfer of a neoplasm from its primary site to lymph nodes or to distant parts of the body by way of the lymphatic system. "Univariate analysis showed that Breslow thickness, Clark level, lymphatic metastasis, distant metastasis, clinical stage, and RNF128 staining were associated with OS and recurrence rates." (PMID 30832692, 2019).
Obesity (1 paper, 2026). Accumulation of substantial excess body fat. "Overall, adipose ZFP36 emerges as a protective post-transcriptional regulator that limits adipocyte expansion and insulin resistance through the RNF128–Sirt1 axis, and its downregulation in obesity contributes to worsening metabolic outcomes." (PMID 41596407, 2026). "Future studies should focus on further elucidating the downstream effects of dysregulated lipolysis in the context of obesity-related pathologies, as well as exploring potential therapeutic interventions targeting the ZFP36/RNF128/Sirt1 pathway to mitigate metabolic dysfunction." (PMID 41596407, 2026).
type 1 diabetes mellitus (1 paper, 2013). A chronic condition characterized by minimal or absent production of insulin by the pancreas. "RNF128 encodes a type I transmembrane protein located in the endocytic pathway and its expression significantly inhibited activation-induced IL4 and IL2 that are involved in type I diabetes mellitus pathway (KEGG: hsa04940)." (PMID 24344781, 2013).
tumor (16 papers, 2013 to 2025). "The up‐regulated genes in tumor‐infiltrating myeloid cells in RARα‐KO mice included Rnf128, Cd36, Nos2, Prdx1, Cd274, and H2‐Q4, associated with the immune‐activating phenotype." (PMID 40068101, 2025). "Meanwhile, we further investigated the role of RNF128 in vivo through subcutaneous tumor formation in nude mice." (PMID 40253377, 2025). "Recent studies have shown that low expression of RNF128 in some tumors promotes tumor progression through the Wnt/β-catenin pathway." (PMID 40253377, 2025). "Taken together, our study reports for the first time that RNF128 acts as a tumor promoter to inhibit autophagy-dependent ferroptosis in GCs by targeting Beclin1." (PMID 40253377, 2025). "We found that RNF128 was closely related to tumor xenograft formation in nude mice, and these results confirmed that the tumor volume and weight in the shRNF128 group were lower than those in the shNC control group." (PMID 36644633, 2022). "To further detect the roles of CD44 and CTTN in RNF128-induced tumor progression, we interfered CD44 or CTTN expression in M14-shRNF128 cells to determine the changes in cellular EMT and stemness." (PMID 30832692, 2019). "However, RNF128 is upregulated and promotes malignant tumor progression through the Hippo and epidermal growth factor receptor/MEK/extracellular signal-regulated kinase pathways." (PMID 40253377, 2025). "In vivo, a xenograft tumor model was used to detect the effect of RNF128 on tumor growth." (PMID 36644633, 2022). "Then, we performed further experiments by western blotting and immunohistochemistry of nude mouse tumor tissues, which showed that RNF128 knockdown resulted in elevated expression of MST and increased phosphorylation of LATS and YAP, while the expression of YAP and TAZ was decreased." (PMID 36644633, 2022). "However, recent studies suggest that RNF128 plays an essential role in tumor occurrence and development." (PMID 33962392, 2021). "In this study, we found that RNF128 knockdown increased autophagic flux and autophagosome production, which may be a potential mechanism through which RNF128 inhibits ferroptosis and promotes tumor progression." (PMID 40253377, 2025). "A previous report demonstrated that RNF128 expression was significantly downregulated in CRC tissues and inhibited the tumor behavior of CRC cells by inhibiting the Wnt/β-catenin pathway." (PMID 36644633, 2022). "As reported, TPPP3, DOCK2, and EIF3H act as oncogenes by suppressing apoptosis of cancer cells, while RNF128, DAPK1, and SYT7 function as tumor suppressors by promoting apoptosis of many types of cancer cells." (PMID 33509274, 2021).
cancer (11 papers, 2019 to 2025). A tumor composed of atypical neoplastic, often pleomorphic cells that invade other tissues. "It was reported that RNF128 functions as an E3 ligase and involved in promoting invasion and metastasis in several types of cancer." (PMID 35820925, 2022). "Previous studies have demonstrated that RNF128 plays different roles in various cancers." (PMID 36644633, 2022). "RNF128 regulates the EGFR/MAPK/MMP-2 pathway to drive these aggressive cancer features in ESCC." (PMID 31216681, 2019). "It is noteworthy, however, that RNF128, SLC16A1, SPRED1, TNRC6B, and TTK are novel in that they are found only among the candidate cancer genes identified by forward genetic screens in mice or among the genes whose expression changes in cancer." (PMID 33427197, 2021). "Taken together, these results suggested that hnRNP A2B1 regulated the pre-mRNA splicing of pro-apoptosis genes (DAPK1, SYT7, and RNF128) and anti-apoptosis genes (EIF3H, TPPP3, and DOCK2), thus leading to the suppression of apoptosis of cancer stem cells." (PMID 33509274, 2021). "Based on experimental data and the cancer genome profiling data, it is reasonable to infer that RNF128 acts as a promoter, not a suppressor, during CRC progression and that RNF128 knockdown inhibits the proliferation, migration and invasion of CRC cells." (PMID 36644633, 2022). "To ascertain whether there is a causative relationship between RNF128 expression and an altered cancer phenotype in ESCC, we selected KYSE150 and KYSE410 cells with relatively low RNF128 expression to construct cell lines with RNF128 stably overexpressing." (PMID 31216681, 2019).
inflammatory myopathies (1 paper, 2022). "In inflammatory myopathies, GRN, MVP and NFYB showed high diagnostic value, while RNF128, ERP29 and KPNA3 showed poor diagnostic value, indicating high inflammation activation but little involvement of protein homeostasis." (PMID 36203997, 2022).
RNF128 also shares sentences with these, for which no sentence is quoted: autoimmune disease (4 papers); infection (4); filariasis (2); lymphoma (2); allergic asthma (1); atherosclerosis (1); cervical adenocarcinoma (1); cervical cancer (1); Chagas disease (1); esophageal carcinoma (1); gastric cancer (1); GI) tumors (1); glioma (1); hearing loss (1); helminth infections (1); inflammatory bowel disease (1); lupus (1); maturity onset diabetes (1); parasitemia (1); prostate carcinoma (1); schistosomiasis (1); steatosis (1).